APP (amyloid beta precursor protein)
Diseases named in the same sentence as APP in open-access papers (continued):
Sharing a sentence is not in itself a finding about the gene and the disease.
infection (79 papers, 2005 to 2026). The state of being infected such as from the introduction of a foreign agent such as serum, vaccine, antigenic substance or organism. "Western blotting (WB) revealed that infection with either virus strain caused a decrease in both full-length APP and its CTF products." (PMID 37454116, 2023). "Moreover, the ingenuity pathway analysis revealed protein molecules such as VLDLR, MBP and APP that are associated with altered profile of cholesterol, fatty acids and triglycerides with infection-related CNS disorders." (PMID 37876925, 2023). "In Tg2576 transgenic mice (the Swedish APP mutation), T. gondii infection in fact reduces cerebral beta-amyloid deposition and increases the levels of anti-inflammatory cytokines, effects attributed to the immunosuppressant effects of infection." (PMID 23533776, 2013). "First, a primary hippocampal neuronal cell model of SV2A overexpression was constructed by infection with SV2Aoe lentivirus, and the levels of APP metabolites were detected in the cell supernatant." (PMID 41521688, 2026). "Somewhat decreased probability of survival was noticed in APP/PS1 mice as two mice died during the infection (3 and 7 WPI, p = 0.05)." (PMID 40214165, 2025). "An overview of the behavioral data suggests that prior to and immediately after infection, APP/PS1 exhibited normal locomotor activity." (PMID 40214165, 2025). "In contrast, in OTSCs from APP KO animals, a dense infection led to depressed AMPAR-mediated EPSCs, but only in neurons infected with C99, indicating that the C99 fragment of APP contributes to Aβ-mediated depression of AMPAR-mediated currents." (PMID 40654986, 2025). "Western-blot (WB) detection of APP showed decreased accumulation of the precursor during the course of infection." (PMID 36898995, 2023). "We have pointed out a modification of the APP post-translational maturation during the course of infection leading to a production of APP-derived peptides preferentially through activation of the amyloid pathway." (PMID 36898995, 2023). "Quantification of the APP transcripts by RT-qPCR showed that their amount decreased progressively during the course of infection." (PMID 36898995, 2023). "After infection, APP and BACE1 expression levels of fCBO were increased whereas γ-secretase complex proteins including PSEN1/2 levels were not." (PMID 36697403, 2023). "APP transcription is up-regulated as a consequence of infections, while DNA strand breaks are induced during neuroinflammation and oxidative stress, and are linked with AD pathology from early stages onwards." (PMID 36395147, 2022). "Case reports of APP and PSEN mutation carriers detailed the presence of severe infections, often times pneumonia, at the end stage of life." (PMID 35517047, 2022). "Studies indicate that infection induces the activation of a calcium ion-dependent signaling pathway that induces phosphorylation of the amyloid precursor protein (APP)." (PMID 36363754, 2022). "In terms of the β amyloid deposition, precursor proteins (APP) were elevated after P gingivalis or P gingivalis LPS infection." (PMID 35244967, 2022). "Because of this, Aβ production, in part, is a detrimental side effect of a viral evasion mechanism to escape restriction to late-stage infection mediated by APP, but it results in neurotoxic effects." (PMID 34452054, 2021). "Combined with inflammatory responses with infection and Tat cytotoxicity, Gag-mediated APP processing, and Aβ production are likely important contributing factors to the overall complexity of HAND pathogenesis." (PMID 34452054, 2021). "In this study, we designed an epitope-based vaccine combined with inactivated bacteria to prevent APP cross infection." (PMID 32642871, 2020). "Instead, APP-bAS, a TSS located more upstream to APP-5′AS, is selectively enriched in monocyte-derived macrophages upon infection and in various brain structures (substantia nigra, striatum, amygdala, thalamus, and cortex) mainly from newborn." (PMID 30610612, 2019).
infection (continued). "Specifically, the data suggest that infection by Chlamydia pneumoniae promotes the pro-amyloidogenic pathway of APP processing by manipulating the expression and activity of the major secretases involved in generating toxic and nontoxic fragments of APP." (PMID 30786875, 2019). "Relative to control brains, we found significantly higher expression of APP mRNA at all timepoints examined after infection out to 10 days." (PMID 30610193, 2019). "We also measured APP by western blot from the same brains and confirmed a progressive, more than threefold increase in APP production by day 14 following infection with C. albicans." (PMID 30610193, 2019). "This study is aimed at investigating the effects of infection by Cpn on genes and the gene products involved in the processing of APP to produce Aβ, which is a major characteristic of AD pathology." (PMID 30786875, 2019). "Because of this, Aβ production is at least in part a detrimental side effect of a viral evasion mechanism to escape a restriction to late-stage infection that is imposed by APP but that results in neurotoxic effects." (PMID 30359460, 2018). "Combined with inflammatory responses to infection and Tat cytotoxicity, Gag-mediated APP processing and Aβ production are likely to be an important contributing factor to the overall complexity of HAND." (PMID 30359460, 2018). "Seven days after infection, expression of hAPP increased the total content of APP by about 1.6 fold (159.6 ± 33%)." (PMID 28337033, 2017). "After synchronous infection most nascent VP26-GFP-labeled viral particles in the cytoplasm co-localize with APP (72.8+/−6.7%) and travel together with APP inside living cells (81.1+/−28.9%)." (PMID 21483850, 2011). "The increased staining for APP and its redistribution after infection was still apparent in cells infected with gEnull virus." (PMID 21483850, 2011). "We found a dose-dependent increase in apoptosis with overexpression of intracellular APP or S100B through lentiviral infection or transient transfection into control HNPs." (PMID 21779383, 2011). "Altogether, these results suggest that infection earlier in life with HSV in the peripheral nervous system, with subsequent infection in CNS, leads to activation of the immune system, altering APP metabolism." (PMID 22216291, 2011). "Although cell enzymes clearly participate in the post-infection APP processing, the fact that the APP-F45 was unaffected by the β- and γ-secretase inhibitors strongly suggests that other mechanisms are also involved." (PMID 21085580, 2010). "Measurement of luciferase activity in cells harvested at different times post-infection (p.i.)revealed time-dependent increases in APP-Gal4 cleavage." (PMID 21085580, 2010). "It is possible to speculate that, while repeated cycles of replication would cause only mild and self-limiting infections, their repeated triggering of APP processing could cause intra- and extracellular accumulation of Aβ and the intranuclear transport of other neurotoxic APP fragments." (PMID 21085580, 2010). "Z-VAD appeared to be the most efficient suppressor of post infection APP cleavage in the luciferase assay." (PMID 21085580, 2010). "Fischer 344 rats expressing human APP driven by the ubiquitin-C promoter were generated via lentiviral vector infection of Fischer 344 zygotes." (PMID 18302776, 2008). "These in vitro findings were furthersupported by experiments using mature neurons derived from human pluripotentstem cells, which showed an increased accumulation of amyloid precursorprotein (APP) aggregates upon infection with HSV-1 or exposure tothe OspA surface protein from B. burgdorferi." (PMID 40859932, 2025). "Interestingly, our results demonstrated that interaction scores of some paired ligands and receptors (e.g., ANXA1_FPR1, CD74_APP, CD74_COPA, CXCL1_CXCR1, CXCL2_CXCR2, and HLA-F_LILRB2) were significantly increased after infection." (PMID 37087411, 2023).
infection (continued). "Moreover, to evade this restriction, HIV-1 Gag increases APP processing but in doing so, infection increases the production of neurotoxic APP-derived amyloids." (PMID 37454116, 2023). "Then we have analyzed the effect of infection on APP metabolism." (PMID 36898995, 2023). "In particular we have characterized the appearance of APP-derived isoforms following infection." (PMID 36898995, 2023). "APP was upregulated in the infection by alphaviruses (ChikV and MayV) and downregulated in the OroV DEG data." (PMID 36423114, 2022). "To determine where in the brain enhanced production of APP was occurring, we performed fluorescent immunohistochemistry for APP on sections of brain from wild-type mice 4 days after infection with C. albicans using an antibody that only recognizes APP and not Aβ." (PMID 30610193, 2019). "Our data indicating that the ratio of sAPPβ per total sAPP (sAPPα and sAPPβ) was significantly increased in Cpn-infected astrocytes at 48 and 72 hpi further supports the conclusion that APP processing favored the pro-amyloidogenic pathway as the infection progressed." (PMID 30786875, 2019). "This demonstrated that APP mediated the effects of secretase inhibitors on infection, and that APP’s antiviral activity could be harnessed using secretase inhibitors to suppress HIV-1 replication." (PMID 29142315, 2017). "Moreover, combined with inflammatory responses to infection and cytotoxicity of proteins like Tat, Gag-mediated APP processing and production of Aβ would be an important contributing factor to the overall process of HIV-1-induced neurodegeneration." (PMID 29142315, 2017). "One month after stereotaxic infection in the CA3 region of 5-month-old APP/PS1 mice, a few GFP-positive CA3 PCs (shA2AR+, expressing the shRNA) could be identified in hippocampal slices." (PMID 27312972, 2016). "Given that APP is substrate for several kinases including GSK-3, JNK and Cdk-5, we studied their involvement in HSV-1-induced APP phosphorylation by adding specific kinase inhibitors to the culture medium of infected cells during the entire post-infection (p.i.)time." (PMID 26487282, 2015). "Hence infection with HSV1 and association of APP with viral particles affects the dynamic movements of emerging viral particles as well as of cellular APP-vesicles." (PMID 21483850, 2011). "On the other hand, when cells were infected with an HSV-1 mutant (R3616, referred to hereafter as Δγ34.5) that is deleted in both copies of the UL34.5 gene, APP mRNA accumulated in the early phases of infection (4 h p.i.)probably as a consequence of the impaired translation." (PMID 21085580, 2010). "To determine whether post-infection APP processing yielded fragments that were secreted into the extracellular space, we subjected TCA-precipitated proteins from cell-conditioned culture medium to western blot analysis." (PMID 21085580, 2010). "Interestingly, local cortical dysplasias can be infection-mediated and are observed in 68% of triple APP/APLP KO-mice." (PMID 20209079, 2010). "Active infection of brain cells with other agents might lead to the same APP effects, but until or unless they are shown to be present, they can not be proposed as possible factors in AD." (PMID 16109164, 2005). "Another way in which infection might affect amyloid biochemistry is suggested by studies demonstrating that Aβ or APP are upregulated in response to a wide range of injurious stimuli, including head injury, stroke or HIV infection." (PMID 16109164, 2005). "However, following infection, proteolytic processing may shift APP and amylin toward amyloidogenesis, resulting in fibrils that entrap microbes, mirroring other antimicrobial peptides in the innate immune system." (PMID 40731182, 2025). "While our prior work established that HIV-1 increased APP processing to evade its antiviral effects, how infection impacts amyloidogenic versus non-amyloidogenic CTFs and the underlying mechanism by which APP inhibits infection remain unknown." (PMID 37454116, 2023).
infection (continued). "Therefore, investigating the effect of infection by Cpn on the processing of APP by astrocytes is invaluable in modeling potential mechanisms by which Cpn may trigger sporadic AD pathology, especially over time." (PMID 30786875, 2019). "Since cleavage at the β-site of APP is a stress response (particularly to infection – see later) and suppression of inflammatory stress is protective of aging vasculature, it may be that A673T acts to reduce chronic inflammatory stress levels and preserve vascular health." (PMID 30150923, 2018). "It was observed that peripheral infection increased the deposition of Aβ in the brain, which was associated with increased T cell infiltration and microglial activation in older, but not younger, APP/PS1 mice." (PMID 28259169, 2017). "However, peripheral inflammation, aging, or AD pathology could disrupt this barrier integrity, allowing activated macrophages in APP/PS1 mice or infection-induced inflammatory cells to breach the barrier and infiltrate the parenchyma, and exacerbate neuroinflammatory cascades." (PMID 40450296, 2025). "Studies on young mice reported that APP genes, especially the MHCII genes, play an important role in ISC fate decision and in remodeling crypt and lamina propria cell compositions upon infection and in disease models." (PMID 37777550, 2023). "In vitro observations confirmed that HSV1 infection increased intracellular Aβ levels and activity of BACE1, the enzyme cleaving Aβ from APP." (PMID 36395147, 2022). "By analyzing the downstream effects of the SARS-CoV-2 upstream regulators on ACE2 expression, found using the infection by SARS coronavirus node, the results indicated inverse modulation of APP expression." (PMID 35163117, 2022). "In vitro infection with HSV1 has been shown to affect processing and distribution of APP (amyloid precursor protein), the precursor to neurotoxic Aβ, by multiple mechanisms." (PMID 32555685, 2020). "We are the first to describe the design and expression of the RTA protein, which was used to immunize mice in combination with inactivated APP and protected them against APP1 and APP5b infection." (PMID 32642871, 2020). "PRR was knocked down by infection of MC3T3 cells (an osteoblastic cell line that expresses PRR, APP and BACE1) with shRNA-PRR lentivirus." (PMID 31108937, 2019). "Interfering with HIV-1’s evasion of APP-mediated restriction also suppresses HIV-1 spread, offering a potential strategy to both treat infection and prevent HAND." (PMID 29142315, 2017). "Other relevant, harmful effects of infection include the following: dynamic interactions between HSV-1 and amyloid precursor protein (APP), which would affect both viral and APP transport." (PMID 25535510, 2014). "APP foci colocalise with sites of opportunistic infection in HIV dementia patients, including sites of herpes virus (cytomegalovirus) infection." (PMID 16109164, 2005). "We have performed both oral and intracerebral routes of infection with periodontal and non-periodontal bacteria in APP TgCRND8 mouse models of AD." (PMID 35328748, 2022). "We also evaluated the data in multiple ways and found no changes in APP expression and amyloid deposition in mice with peripheral infection but infection altered astrocytosis." (PMID 35328748, 2022). "The transcripts of APP, ADAM10, BACE1, and subunits of the γ-secretase complex (PSEN1, PSEN2 APH1A and NCSTN) were significantly upregulated (p < 0.05) in at least one of the 4 investigated timepoints post-infection." (PMID 30786875, 2019). "If the increase in APP mRNA observed in Cpn-infected astrocytes at 6 hpi signals an increase in APP protein, then the surplus APP within the cell is processed by the non-amyloidogenic pathway at an early time of infection." (PMID 30786875, 2019).
infection (continued). "Among the top hits identified as a Salmonella ligand for APP was integration host factor-α (IhfA) – a protein involved in the regulation of Salmonella SPI-1, a pathogenicity island that contains proteases used for infection." (PMID 30072965, 2018). "By synchronizing infection and performing live imaging of VP26-GFP-labeled capsids in cells expressing fluorescently labeled APP, we report results that provide new insights into the interaction between viral and host cell components during transit of virus to the surface." (PMID 21483850, 2011). "VP26-GFP particles traveled both with and without APP, although those without detectible APP were in the minority at the early time points after infection reported here." (PMID 21483850, 2011). "One hepatic protein, fetuin-A, has previously been suggested either as a negative or positive APP following infection- or injury-elicited inflammation." (PMID 21347455, 2011). "A similar pattern of APP-F secretion was also found at earlier time-points (12 h p.i.), thus indicating that the HSV-1-induced APP processing we observed is not simply an artifact due to the late infection time." (PMID 21085580, 2010). "The surprising increase in amount of the 55 kDa C-terminal APP fragment in infected cells shows that processing of APP as well as its synthesis is affected by HSV1, that this occurs within 6 h of infection, and that the level increases with time after infection up to at least 9 h." (PMID 16109164, 2005). "In addition, there was no increase in axonal damage (beta APP positive axons) within the spinal cord of CD28-knockout mice in the early phase of TMEV-infection at 14 dpi." (PMID 37090733, 2023). "This suggests that non-amyloidogenic APP processing is not inhibitory to infection and if anything, may promote infection as discussed later." (PMID 37454116, 2023). "Moreover, as in WT mice, infection with H3N2 IAV did not further significantly increase microglial density in the hippocampus of infected APP/PS1 mice compared to non-infected APP/PS1 mice (Δ 5%, p = 0.71), [Two-way ANOVA FInfection = 0.0018, p = 0.96]." (PMID 33994946, 2021). "Could it be that expulsion of “free” cytosolic iron from neurons via increased expression of APP promotes brain survival in the face of infection by allowing absorption of the iron by adjacent non-neuronal cells better equipped to sequester it?" (PMID 30150923, 2018). "In vitro studies have demonstrated that HSV-1 triggers amyloid precursor protein (APP) processing, resulting in the production of amyloid β (Aβ) via β- and γ-secretases, and murine studies have shown that APOE4-expressing mice have a significantly enhanced viral burden after infection with HSV-1." (PMID 28259169, 2017). "Interestingly, secreted APP levels in medium from HSV-1-infected cell cultures appeared lower than those from control cultures, suggesting that their production diminishes after infection." (PMID 21085580, 2010). "In addition to its neuronal expression, APP is synthesized in peripheral organs; thus, the soluble APP in CSF could, at least in part, be from the peripheral blood, given that the integrity of the BBB is compromised during infection and inflammation with increased permeability to proteins." (PMID 35634471, 2022). "Based on our findings, we hypothesize that mutations in APP, MAPT, and PSEN1 genes yield a compounding effect with age, triggering biological changes which initiate an inflammatory response that mimics the effects of LPS stimulation, despite the absence of infection." (PMID 38909241, 2024). "There are currently commercial vaccines made from toxins such as Porcilis APP (MSD Animal Health), Ingelvac® APPX (Boehringer Ingelheim), and Coglapix® (Ceva), but none have managed to control infection by App." (PMID 38098987, 2023).
infection (continued). "The contribution of these lncRNAs to cell–trait pairs is also supported by their dynamic upregulation during iPSC (induced pluripotent stem cells) differentiation to neurons (APP and MAPT antisense) or in immune cells upon infection (C9orf72 and LRRK2 antisense) (data not shown)." (PMID 30610612, 2019).